MSLN (mesothelin)
Diseases named in the same sentence as MSLN in open-access papers (continued):
Sharing a sentence is not in itself a finding about the gene and the disease.
tumor (continued). "Soluble MSLN (SMRP) measured from serum samples has a high specificity but lacks sensitivity for MPM diagnosis, screening, and prognosis; however, it is a useful biomarker to monitor response to therapy because its expression is associated with tumor volume." (PMID 34439085, 2021). "Reports have indicated that MSLN may be involved in tumor progression and metastasis through EMT activation." (PMID 33196692, 2020). "Utilizing Mesothelin as a tumor target is therefore afflicted with unwanted cross-reactivity." (PMID 32815024, 2020). "The immunogenicity of MSLN was determined to be related to its high expression on tumor cells." (PMID 32983962, 2020). "Moreover, dual-receptor CAR-modified T cells that simultaneously recognize CEA and MSLN were designed to attenuate the “on-target, off-tumour” toxicity." (PMID 33008426, 2020). "We examined the effect of ERC/mesothelin overexpression on mouse survival and tumor phenotype." (PMID 32677949, 2020). "Integrin αvβ6, CEACAM5, and mesothelin demonstrated membrane-bound tumor cell expression." (PMID 33004930, 2020). "Whether an increased Mesothelin expression provides a growth advantage for the tumor or has an impact on the prognosis is discussed controversially." (PMID 32815024, 2020). "Specifically, the limited benefit of targeting MSLN may be examined in the context of the tumor-specific state of the downstream mediators suggested by our study." (PMID 32616712, 2020). "MSLN is a transmembrane glycoprotein relatively specific to mesothelial cells that line body cavities including the peritoneum, but is also highly expressed in many tumour cells including mesothelioma, ovarian and pancreatic cancer." (PMID 32937961, 2020). "In addition, several studies have suggested a function for MSLN in cell survival, invasion, tumor progression, and chemoresistance." (PMID 32612258, 2020). "However, there is little difference in MSLN expression between the leading edge of the tumor and the tumor surface." (PMID 33196692, 2020). "However, some CAR-T cell therapies in clinical trials are targeting antigens that are expressed in both tumor and normal tissues (e.g. mesothelin, GD2, and IL13Rα2) and are demonstrating favorable responses without obvious adverse effects." (PMID 32228854, 2020). "Finally, MSLN is emerging as an attractive target for cancer immunotherapy, considering its overexpression in several tumor contexts." (PMID 32612258, 2020). "Our data also identified many novel drug agents that demonstrate anti-tumour activity in vitro and in vivo, and these include the anti-mesothelin immunotoxin SS1 (dsFv)-PE38, the PI3K inhibitor AZD-6482 and the cyclin-dependent kinase inhibitors variolin B, meriolin, alsterpaullone and dinaciclib." (PMID 32899298, 2020). "Future clinical trials may benefit from a more rigorous selection of appropriate patients based on the level of Mesothelin expression in their tumor tissue." (PMID 32815024, 2020). "Overall, our results suggest that using the MG1122-B bsAb to promote T-cell activity against MSLN-expressing tumor cells could be a useful treatment strategy for solid tumors." (PMID 32143496, 2020). "The expression of MSLN isoforms in the vast majority of OC, as well as in other tumors, indicates that they may have biological functions in tumor cells." (PMID 32983962, 2020). "Importantly, besides these cancers, MSLN overexpression was also observed in 80 to 85% of PDAC-derived tumor samples." (PMID 32517181, 2020). "miR-21-5p indeed acts as a tumor suppressor miRNA since it negatively regulates MSLN expression." (PMID 32517181, 2020). "The findings are confirmed for mesothelin as alternative tumor antigen." (PMID 32581215, 2020). "A cleavable antibody specifically targeting mesothelin+ tumor cells and containing the chemoattractant CXCL16, which binds CXCR6, improved NK cell infiltration after adoptive transfer, which reduced tumor burden and prolonged survival in orthotopic or metastatic PDA murine models." (PMID 33584701, 2020).
tumor (continued). "In a tumor context, MSLN plays an important role in survival, proliferation, and migration/invasion of cancer cells as well as in drug resistance, potentially through the Wnt/NF-κB/PI3K/Akt signaling pathways and/or by facilitating the anchorage-independent growth." (PMID 31354732, 2019). "The MSLN gene is overexpressed in many cancers and likely to play a role in tumor progression." (PMID 31033411, 2019). "One example of this is mesothelin, a tumor differentiation antigen." (PMID 30736355, 2019). "One study employed a vaccinia virus to deliver the chemokine CXCL11 intratumorally in a subcutaneous mouse model of MPM and observed significantly increased levels of T cell infiltration and anti-tumor efficacy after intravenous mesothelin-directed CAR T cell injection." (PMID 30804938, 2019). "BAY2287411, a thorium-227-labeled antibody-chelator conjugate, was administered to patients with tumors known to express MSLN to evaluate the safety, tolerability, maximum tolerated dose, PK, anti-tumor activity and recommended dose for further clinical development (NCT03507452)." (PMID 31463062, 2019). "The binding of amatuximab to MSLN expressed on tumor cell surfaces leads to ADCC." (PMID 31463062, 2019). "The value of soluble MSLN in diagnosis and the prediction of cancer progression remains to be determined, and its combination with other tumor markers may be more precise for diagnosis." (PMID 31463062, 2019). "MSLN-redirected CAR-T cells are also associated with the “on target, off tumor” issue." (PMID 31463062, 2019). "Notably, MSLN-targeting CAR-T cells were able to lyse primary tumor cells and elicit a systemic antitumor immune response by inducing epitope spreading." (PMID 31463062, 2019). "Thus, for constructs directed against mesothelin, there is concern for “on-target off-tumor” toxicity." (PMID 30736355, 2019). "For the first time, we proposed a dual-receptor CAR specific for FITC and MSLN, and its cytotoxicity was effectively controlled with the use of two combined inputs, a switch molecule and cognate tumor cells expressing integrin αvβ3 and MSLN, thereby enhancing the safety of CAR-T cell therapy." (PMID 29558951, 2018). "In addition, cognate tumor cells expressing MSLN and integrin αvβ3 are required for sdCAR-T cell function." (PMID 29558951, 2018). "Tumor targeting is a complex process and, furthermore, modulation of MSLN shedding could have an influence on drug kinetics in both circulation and tumor tissue." (PMID 30134520, 2018). "Recent studies have revealed that mesothelin may play an important role in cancer survival/proliferation, tumor progression, and drug resistance through the Wnt/NF-kB/PI3K/Akt signaling pathway." (PMID 30140382, 2018). "In addition, there was no T cell activation for the non-cognate tumor cell line (K562 cell or CEA+ K562 cell) in contrast to the significant activation for cognate tumor cells (MSLN+ K562), thereby showing specific targeting activity of sdCAR-T cells." (PMID 29558951, 2018). "MSLN is a membrane glycoprotein of 40 kDa that is actively internalized into the cell's cytosol as well as shed from the tumor cell surface, generating soluble MSLN in the tumor's interstitial space and blood circulation with its concentrations proportional to the size of tumor." (PMID 29720923, 2018). "However, the combination of i.t. anti-mesothelin immunotoxins with systemic anti-CTLA-4 induced tumor regression in the majority of the mice, supporting the idea that the combination of the two outperforms each treatment alone." (PMID 30441807, 2018). "Similarly, for sdCAR-T cells, a remarkable upregulation of CD69, an activation marker presented on T cell surfaces, was observed only in the presence of cognate tumor cells (MSLN+ K562) and the switch molecule FHBM." (PMID 29558951, 2018).
tumor (continued). "Although only a minority of the cohort (n = 28) could be reassessed using PET imaging, due to prior pleurodesis or surgery, the change in both metabolic activity (TGV) and tumour bulk strongly correlated with change in mesothelin levels (p < 0.001)." (PMID 29454314, 2018). "While mesothelin is a tumor associated antigen that can be detected in Panc02 cells grown in vitro or as a tumor grown in the mouse, it is not a highly abundant protein." (PMID 29474384, 2018). "In this review, the involvement of mesothelin (MSLN) in the tumor microenvironment is discussed." (PMID 30134520, 2018). "Furthermore, MSLN is reported to play a role in cell adhesion, tumor progression, and chemoresistance." (PMID 30134520, 2018). "It has also been reported that mesothelin may play an important role in cell adhesion, cell proliferation and migration, tumor progression, and resistance to chemotherapy." (PMID 30140382, 2018). "Since the Panc02 tumors grow rapidly, we tested whether inducing an immune response to mesothelin prior to tumor induction would be protective against tumor growth." (PMID 29474384, 2018). "Furthermore, amounts of Th1 cytokines secreted in response to mesothelin+ tumor cells were positively correlated with mesothelin expression levels." (PMID 29568387, 2018). "Prior to testing of individual target mutant epitopes, identified by tumor exome sequencing, T-cell recognition was gauged using a broad panel of antigens associated with common viral pathogens (e.g. CMV, EBV, Flu), tumor–associated antigens (e.g. NY-ESO- 1, Melan-A/MART-1, survivin, mesothelin)." (PMID 30400835, 2018). "Conversely, the exact function of MSLN in tumor progression remains unclear; however, understanding the importance of CA125:mesothelin binding may lead to novel therapies to control ovarian peritoneal metastasis." (PMID 30134520, 2018). "The ADC anetumab ravtansine, a fully human anti-mesothelin antibody (MF-T) coupled via a reducible disulfide linker to a microtubule-targeting toxophore DM4, binds to mesothelin with high affinity and delivers the microtubule inhibitor DM4 to mesothelin-positive tumor cells." (PMID 30344925, 2018). "This fact may be especially useful because irradiation of tumor cells enhances the expression of mesothelin, so that an anti-mesothelin vaccine may be an effective combination with irradiation." (PMID 29474384, 2018). "In addition, dCAR-T cells cleared cognate tumor cells with a similar cytotoxicity comparable to that of conventional CAR-T cells (CEA-CAR T or MSLN-CAR T) in in vitro and in vivo experiments, thereby promoting their applications." (PMID 30103775, 2018). "Next, we evaluated the ability of two distinct tumor-associated antigens (i.e., CEA and MSLN) to redirect dCAR-T cells to cognate tumor cell AsPC-1, using antigen-negative PANC-1 cell line as a control." (PMID 30103775, 2018). "Indeed, we tested the effect of mesothelin expression in the presence of an intact host immune system and found that overexpression of mesothelin unexpectedly decreased metastases and even inhibited tumor formation in vivo in immunocompetent mice." (PMID 29474384, 2018). "For the single-receptor CAR bearing one signal pathway in this research, including Cζ-CAR and MBB-CAR, effector cells had no significant activation activity and did not exert remarkable cytotoxicity even in the presence of cognate tumor cells (AsPC-1) expressing both MSLN and CEA." (PMID 30103775, 2018). "To focus CD47 blockade on tumor cells, we generated two bispecific antibodies (biAbs) pairing a high affinity arm targeting a tumor associated antigen (TAA), i.e., CD19 or mesothelin (MSLN), to an optimized lower affinity arm targeting CD47 and investigated their efficacy in xenograft tumor models." (PMID 30400822, 2018). "Thus, the likelihood of expressing calretinin and mesothelin simultaneously would increase with the growth and stage of the tumor." (PMID 30254313, 2018).
tumor (continued). "Moreover, to improve the specificity of CAR-T cells, we also generated the sdCAR-T cell line against cognate tumor cells expressing human mesothelin (MSLN) and integrin αvβ3." (PMID 29558951, 2018). "Anti-mesothelin directed T-cell responses could also be detected in tumor - infiltrating lymphocytes (TIL) isolated from GBM speciments." (PMID 29113296, 2017). "Furthermore, these results suggest that appropriate type of anti-mesothelin antibody should be used when evaluating mesothelin expression in different tumor types." (PMID 28460459, 2017). "MSLN abundance on tumour cells is sufficient for efficient antibody targeting of doxorubicin-loaded EDVs to xenografts, resulting in suppression of tumour growth as well as reducing cell proliferation as shown by Ki67 staining of excised tumours ex vivo." (PMID 29059207, 2017). "Followed by further experimental validation of miRNA::mRNA interaction, this technique identified miR-21-5p as a regulator of MSLN mRNA that may have role in its increased expression and in the proliferation of tumour cells in MPM." (PMID 28125734, 2017). "In addition to regulating tumor formation, our data also suggest the role of MSLN in controlling metastasis." (PMID 28288645, 2017). "Similarly, the insertion of mesothelin into SHIV VLPs also induced significant anti-tumor responses." (PMID 29158984, 2017). "Mesothelin, Ezrin and ENOA have also been linked to tumor metastasis and cancer progression." (PMID 26840568, 2016). "Thus, our data show that the distribution of murine mesothelin is limited to certain cancers similar to human mesothelin expression and suggest the use of certain mouse tumor models for the study of mesothelin." (PMID 26931187, 2016). "We show here that mouse mesothelin is similar to human mesothelin in biochemical characteristics, tumor expression and tissue distribution, suggesting the mouse may be a suitable model for study of mesothelin." (PMID 26931187, 2016). "Mesothelin is a GPI anchored cell surface protein that can promote cancer cell survival and proliferation, while Ezrin plays an important role in cellular processes like cell adhesion and migration and is linked to tumor metastasis." (PMID 26840568, 2016). "Since mesothelin expression is largely limited to cancerous cells in the adult, it may also be an effective target tumor antigen for anti-cancer vaccines or therapies." (PMID 26931187, 2016). "Previous studies demonstrated that soluble mesothelin, with a sensitivity of 50 % and a specificity of 95 %, could be a relevant tumor marker and the baseline serum level of mesothelin is an independent predictor of overall survival." (PMID 27066377, 2016). "This fact may be especially useful because irradiation of tumor cells enhances the expression of mesothelin, so that the combination of these treatment modalities may be synergistic." (PMID 26931187, 2016). "In addition, the large number of samples included in this analysis and the broad spectrum of tumor types allow for robust estimations of predicted MSLN amplification rates." (PMID 26172299, 2015). "Studying mesothelin with molecular imaging in the clinic may be increasingly of interest giving the increment of treatment options tested that use mesothelin as a target and the broad range of tumor that can express mesothelin." (PMID 26536664, 2015). "We applied this method to publicly available expression data of 19,746 unrelated, patient-derived tumor samples to gain more detailed information about the position of MSLN as a generalizable drug target in 41 tumor types and compared this data to currently existing IHC data from literature." (PMID 26172299, 2015). "Therefore we determined overexpression of MSLN across different tumor types with Functional Genomic mRNA (FGM) profiling of a large cancer database." (PMID 26172299, 2015). "In addition, we generated a humanized YP218 Fv that retained full binding affinity for mesothelin-expressing tumor cells." (PMID 25996440, 2015).
tumor (continued). "Moreover, it is not possible determine heterogeneity in expression between tumor cells or to determine which cell type in the tumor tissue expresses MSLN." (PMID 26172299, 2015). "This is the first study to show tumor localization of an anti-mesothelin antibody in humans." (PMID 25756664, 2015). "Finally, vaccination of mice with the Ad5-PK vector resulted in enhanced T-cell-mediated interferon gamma (IFN-γ) release in response to both mesothelin peptide and a tumor line expressing mesothelin." (PMID 25933160, 2015). "Conceptually, SS1P and other mesothelin-targeted therapies might also confer efficacy in other tumor types that over-express mesothelin." (PMID 26028668, 2015). "Tumor tissue samples from 53 patients were assayed for mesothelin expression by IHC." (PMID 25502863, 2015). "This tumor cell line expresses a large number of mesothelin molecules (106/cell)." (PMID 25343405, 2014). "In the present study, we improved the model by incorporating several new features and applied the improved model on two systems, the immunotoxin LMB-2 targeting CD25 of the ATAC-4 cell tumor as well as the original SS1P targeting mesothelin of the A431/H9 cell tumor." (PMID 25343405, 2014). "We have developed a novel protein-based immunotherapy consisting of a fusion of an anti-MSLN scFv of human origin and recombinant mycobacterial heat shock protein 70 that has the ability to adjuvant significant T-cell responses against specific tumor antigens." (PMID 24565018, 2014). "Recently the expression level of MSLN protein was correlated with tumor aggressiveness as well as decreased overall survival of patients with early-stage lung adenocarcinoma, but the molecular mechanism that contributes to these phenotypes are not well understood." (PMID 25118887, 2014). "Furthermore, the analysis of immune infiltrates in human tumors has demonstrated a positive correlation between prognosis and presence of humoral response to pancreatic antigens (MUC-1 and mesothelin) or of tumor-infiltrating T cells." (PMID 23509731, 2013). "Indeed, many proposed blood tumor-markers like mesothelin, carcinoembryonic antigen (CEA) or cancer antigen 125 (CA-125) are glycoproteins of cell surface origin." (PMID 24207061, 2013). "However, the sensitivities of the tumor markers CEA, CA 125, CA 15-3, CYFRA 21-1 and mesothelin strongly depend on the tumor entity." (PMID 24386354, 2013). "Neither the MSLN gene nor its encoded protein changed in tumour at resistance and tumour growth but serum mesothelin was reduced at response and increased at resistance." (PMID 22905093, 2012). "Furthermore, mesothelin-shRNA-transfected cells exhibited a reduced rate of tumor growth under in vivo conditions." (PMID 23034174, 2012). "JoPaca-1 cells express the tumour marker mesothelin and several cytokeratins." (PMID 23152778, 2012). "However, mesothelin-transfected cells exhibited a increased rate of tumor growth under in vivo conditions." (PMID 23034174, 2012). "We hypothesized that that MR engagement by tumor-released mesothelin contributes to macrophage polarization." (PMID 22163010, 2011). "We further hypothesized that tumor-released mesothelin binds to mannose receptor expressed by macrophages via GPI anchor-mannose residues." (PMID 22163010, 2011). "Anti-CRD4-MR scFv #G11 could block the binding of tumor-released mesothelin to mannose receptor and prevent in vitro tumor-induced TAM polarization." (PMID 22163010, 2011). "Lastly, we investigated whether mesothelin resides in tumor-released exosomes, We immunoprecipitated mesothelin from tumor cell supernatants and looked by western blot for the presence of co-immunoprecipitated exosomal proteins TSG101 and ALIX." (PMID 22163010, 2011).